VIP (vasoactive intestinal peptide)
Diseases named in the same sentence as VIP in open-access papers (continued):
Sharing a sentence is not in itself a finding about the gene and the disease.
migraine (continued). "VIP is the first substance that markedly dilates intra- and extracranial arteries; nevertheless, it does not induce migraine, further weakening the hypothesis of a purely vascular origin of migraine." (PMID 37569648, 2023). "So far, selective blockade of VIP has not been studied as a treatment of migraine." (PMID 37370051, 2023). "The authors found that PACAP infusion induced migraine attacks, whereas VIP infusion did not." (PMID 35870898, 2022). "We found no increase in plasma CGRP during VIP-induced migraine attacks (p = 0.219)." (PMID 35432170, 2022). "Anatomically, this could indicate that the effect of both VIP and PACAP occurs is via the VPAC1 receptor in the basal arteries, but the timeline for induction of migraine after VIP and PACAP infusion is quite different, suggesting separate receptors and downstream pathways." (PMID 36387999, 2022). "Other ganglia without barrier protection may also be involved in migraine pathogenesis, and preclinical data has suggested that activation of the sphenopalatine ganglion causes release of PACAP and VIP from its efferent fibers." (PMID 35081902, 2022). "It remains unclear whether the lack of migraine induction can be attributed to the transient vasodilatory response of VIP." (PMID 34488620, 2021). "It remains unclear whether the lack of migraine induction can be attributed to the only transient vasodilatory response after a 20-minute infusion of VIP." (PMID 34357396, 2021). "Further, the short plasma half-life of VIP, two minutes (as compared to 6–10 min of PACAP), could be the cause of its lack of migraine-inducing effects." (PMID 30088106, 2018). "Perhaps the most convincing argument that vasodilation may be an epiphenomenon and not a causative factor in migraine came from a study showing that vasoactive intestinal peptide (VIP) induces vasodilation, but only produced a mild headache, not a migraine." (PMID 30127722, 2018). "Interestingly, the structurally related vasoactive intestinal peptide (VIP) does not induce migraine." (PMID 30238173, 2018). "Although VIP infusion did not induce migraine attacks, VIP levels were elevated in patients with CM who exhibited increased cranial parasympathetic system activity during migraine attacks, as well as patients with EM and patients with CM during interictal periods." (PMID 38612517, 2024). "The rationale was primarily based on a report that VIP could not induce migraine in patients." (PMID 37009867, 2023). "A study investigating the efficiency of CGRP, PACAP, and VIP as migraine biomarkers using blood samples derived from chronic migraineurs, episodic migraineurs, and healthy controls revealed that VIP and PACAP could increase the risk of chronic migraines but not that of recurrent migraines." (PMID 37373239, 2023). "Importantly, VIP does not trigger migraine in migraine patients." (PMID 30596910, 2019). "Although vasodilatation is elicited by a majority of the migraine provoking agents, the vascular response does not seem essential for generating delayed migraine attacks, as robust vasodilators, such as the vasoactive intestinal polypeptide (VIP) or adrenomedullin, do not induce migraine." (PMID 30764776, 2019). "However, unlike PACAP, infusion of VIP does not induce migraine." (PMID 31649062, 2019). "It has been revealed that PACAP-38 may induce migraine-like attacks while VIP does not." (PMID 27475101, 2016). "In a randomized clinical trial that involved the infusion of vasoactive intestinal peptide (VIP) into 12 patients, migraine-like headache was not triggered in migraine patients, although there was vasodilation of the superficial temporal artery." (PMID 38481473, 2024). "The localization of these receptors in relation to VIP and PACAP in migraine-relevant structures has not previously been shown in mice." (PMID 36387999, 2022).
migraine (continued). "MRA studies performed on healthy controls and migraine patients report dilation of the MMA after infusion of CGRP, PACAP-27, PACAP-38, and VIP but no change of the MCA circumference." (PMID 35081902, 2022). "To date, the relationship between VIP and CGRP in humans and its potential relevance to migraine has never been investigated." (PMID 35432170, 2022). "Because VIP has a very low affinity for the PAC1 receptor, it is unlikely that VIP-induced migraine was mediated via this receptor." (PMID 34357396, 2021). "Clinically, plasma samples from pediatric migraine patients without aura were examined to determine the levels of PACAP and VIP compared to the control." (PMID 33653014, 2021). "PACAP-38, but not the related peptide VIP, induces migraine headache in migraineurs suggesting the specific PACAP-receptor, PAC1, as a potential target for migraine treatment." (PMID 30983973, 2019). "In view of the suggested role of PACAP, but not VIP, in migraine, an antibody against the PAC1 receptor (AMG 301) has been developed for the treatment of migraine (Clinical trials identifier: NCT03238781)." (PMID 29500688, 2018). "The PAC1 receptor was proposed as the most relevant PACAP receptor in migraine partly because this is stimulated exclusively by PACAP and not, as the VPAC1 and VPAC2 receptor, also by VIP." (PMID 29500688, 2018). "An interesting aspect to consider is that even though VIP belongs to the same family of peptides as PACAP38, it does not induce migraine attacks in MO patients." (PMID 29453754, 2017). "In contrast, a recent case–control study in a mixed-gender population (predominantly female) reported significantly higher interictal concentrations of CGRP, VIP, and PACAP-38 in patients with migraine with aura compared to those without aura and healthy controls Reference." (PMID 40901673, 2025). "This study therefore suggested that CGRP and NOS mechanisms may interact in migraine, PACAP mechanisms may be somewhat distinct, and VIP likely also does not interact with the CGRP and NOS systems." (PMID 37569369, 2023). "Interestingly, the PAC1 receptor was initially identified as a potential target for migraine and headache disorders as infusion of PACAP, but not VIP, produced migraine-like symptoms." (PMID 36430275, 2022). "Finally, although several vasoactive drugs cause cranial arterial vasodilation and subsequently trigger migraine, including nitroglycerin, CGRP, and PACAP, VIP does not trigger a delayed migraine headache in patients." (PMID 29536279, 2018). "Since VIP was earlier reported not to induce migraine-like headaches, this could suggest that the role of PACAP in migraine is probably through modulation of the trigeminocervical complex via the PAC1 receptor." (PMID 29500688, 2018). "Interestingly, VIP only induces a mild headache and no migraine-like attacks in migraineurs, which leads to the suggestion that PACAP and the PAC1-receptor are key targets for future migraine treatment." (PMID 30983973, 2019).
colitis (51 papers, 2010 to 2025). Inflammation of the colon. "It has been reported that VIP attenuates colitis-associated inflammation and diarrhea after systemic administration, making it a promising therapeutic option for IBD management." (PMID 38342939, 2024). "Impaired VIP signalling was observed in (TNBS)-induced colitis which is associated with a dramatic reduction of slow excitatory synaptic transmission in VIP-expressing secretomotor neurons in the submucosal plexus of guinea-pig." (PMID 34983592, 2022). "Literature data report that an increase in the number of VIP-IR submucosal neurons is associated with a decrease in inflammatory cytokine levels in murine models of colitis treated with GLP-2." (PMID 33238628, 2020). "Using VIP deficient (VIPKO) mice, we investigated VIP’s role in epithelial barrier homeostasis, and susceptibility to colitis." (PMID 25932952, 2015). "Because VIP plays an essential role in regulating colonic mucosal integrity and epithelial barrier homeostasis, alterations in VIP tissue concentration are associated with increased colitis susceptibility." (PMID 32336953, 2020). "VIP regulates colonic crypt cell proliferation, migration, and maturation, as well as secretion of bioactive goblet cell peptides, and promotes tissue repair and homeostasis, thereby controlling susceptibility to colitis." (PMID 25932952, 2015). "Moreover, the current study shows a novel link between VIP and Cdx2 activation; however further studies are required to better understand the relation between VIP, Cdx2, and susceptibility to colitis." (PMID 25932952, 2015). "Furthermore, DSS induced colitis was associated with VIP and VPAC1 receptors." (PMID 34899686, 2021). "Using in vivo and in vitro model systems, we demonstrate that VIP plays an indispensible role in regulating colonic mucosal integrity and epithelial barrier homeostasis and its absence in an appropriate environmental context increases susceptibility to colitis." (PMID 25932952, 2015). "VIP can affect intestinal mucin secretion and intestinal bacterial adhesion by regulating the number and function of intestinal cup cells, and a protective effect of VIP against colitis in mice has been reported in the literature." (PMID 39926427, 2025). "Exogenous VIP administration attenuates colitis by preserving tight junctions and restoring gut homeostasis." (PMID 41303686, 2025). "The lower dose of VIP can increase the severity of colitis in a mouse model of Crohn's disease, found by Newman et al34." (PMID 38342939, 2024). "Another study has shown the role of mast cells and neuropeptides (SP, somatostatin (SS), and vasoactive intestinal peptide (VIP)) in DSS colitis." (PMID 37373085, 2023). "Supplementation of VIP alleviated TNBS colitis in mice, which was accompanied by a reduced number of IMφs as well." (PMID 35593111, 2022). "Strikingly, DCreg cells derived using vasoactive intestinal peptide (DC-VIP) dramatically reduced the severity of TNBS-induced colitis in mice on both a clinical and histopathological level." (PMID 36591309, 2022). "If these proteases led to the increased trypsin-like activity in colon from post-colitis animals measured with fluorogenic substrates, we probably would have observed increased VIP processing by these samples as well." (PMID 34639054, 2021). "A decrease in TH, NPY and VIP expressing CaMG-neurons was also presented for chemically induced colitis in pigs." (PMID 34246257, 2021). "In a TNBS-induced colitis model, the transfer of tolDCs treated with Vasoactive Intestinal Peptide (VIP) significantly improved the clinical and histopathology severity of colitis." (PMID 34361038, 2021). "Vasoactive intestinal peptide (VIP) has immune regulatory functions, and administration of VIP can inhibit experimental colitis." (PMID 34880901, 2021). "VIP protects the distribution and levels of junction proteins (for example, ZO-1, occludin, claudin-3, and claudin-4) against colitis by inhibiting MLCK or PKCε." (PMID 34552687, 2021).
colitis (continued). "Namely, it is known that the administration of VIP (especially using sterically stabilized micelles) is capable of alleviating colitis in mice and showing anti-inflammatory and antidiarrheal effects." (PMID 32998326, 2020). "The results also showed that treatment with LP-YS4 significantly reduced the serum concentrations of ET-1, SP, and IL-10 while significantly increasing those of SS, VIP, and IL-2 in colitis mice (P < 0.05)." (PMID 32849906, 2020). "Vasoactive Intestinal Peptide (VIP), an immunomodulating and anti-inflammatory endogenous hormone, reverses colitis and associated diarrhea in mouse models with sterically stabilized micelles (SSM) nanoformulation." (PMID 32486445, 2020). "In this study, LP-YS4 inhibited colitis by downregulating the levels of ET and SP and upregulating those of SS and VIP." (PMID 32849906, 2020). "The results showed that VIP analogs ameliorated changes in the colon after experimentally induced colitis in rats and reduced necrosis, hyperemia and swelling." (PMID 32998326, 2020). "TLR modulation by VIP was described for the first time in the trinitrobenzene sulfonic acid (TNBS)-induced colitis mouse model, which mimics human Crohn’s disease (CD)." (PMID 31861827, 2019). "Nevertheless, the connection of VIP with animal models of colitis related to IBD has yet to be fully elucidated." (PMID 31559013, 2019). "It is also important to note that VIP has shown beneficial effects in other models of colitis, such as colitis induced by Citrobacter rodentium and the oxazolone-induced colitis." (PMID 31861827, 2019). "Subsequently, genetically modified animal models have been used to clarify the contributions of endogenous VIP and its receptors to the pathogenesis of colitis." (PMID 31559013, 2019). "The first report regarding VIP and colitis is that exogenous VIP improves TNBS-induced colitis in BALB/c mice, most likely via VPAC1 activation with anti-inflammatory and Th1–Th2 switching effects of VIP99." (PMID 31559013, 2019). "Nevertheless, VIP KO mice develop more severe colitis in the DNBS- or DSS-induced colitis models, which is rescued by exogenous VIP treatment." (PMID 31559013, 2019). "Using VIP KO mice, different studies showed an exacerbation or an amelioration of chemically induced colitis." (PMID 31849864, 2019). "For instance, VIP KO developed more severe dinitrobenzene sulfonic acid (DNBS)-induced colitis, exacerbated inflammatory asthma and enhancement of innate and adaptive immune responses in a model of viral infection than wild-type mice." (PMID 31695683, 2019). "Concerning VIP knockout mice, the results using the chemical-induced colitis models are contradictory." (PMID 31861827, 2019). "In the murine TNBS induced colitis model, one study found that VIP reduced the clinical and histopathologic features of colitis, whereas another study did not." (PMID 30252907, 2018). "A previous study demonstrated that prophylactic VIP treatment decreased the C. rodentium induced colitis at 10 days post infection, although bacterial attachment was not affected." (PMID 30252907, 2018). "In the murine C. rodentium infection model, we assessed the impact of VIP on colitis, mitochondrial function, pathogen- and colitis burden." (PMID 30252907, 2018). "Treatment of experimental colitis with VIP was shown to effectively reduce severity of 2,4,6-trinitrobenzene sulfonic acid induced colitis in mice." (PMID 29232715, 2017). "Administration of VIP induces a remarkable amelioration of TNBS-induced colitis through activation of VPAC1." (PMID 26635804, 2015). "Taken together, these data suggest that VIP promotes epithelial barrier homeostasis, integrity and function, thus reducing the severity of colitis and enhancing IEC recovery." (PMID 25932952, 2015). "The therapeutic potential of VIP in CD is indeed supported by the beneficial effects of VIP in TNBS-induced colitis, an experimental model of CD." (PMID 26635804, 2015).
colitis (continued). "They showed that although VIP KO mice developed a milder clinical response to TNBS-induced colitis than WT mice, the histological scores and cytokine levels in the colon were similar between mouse strains." (PMID 25932952, 2015). "In experimental trinitrobenzene sulfonic acid (TNBS) induced colitis, VIP exerted prophylactic and therapeutic effects, hence providing evidence for anti-inflammatory effects of PACAP and VIP in the intestinal tract." (PMID 25238233, 2014). "There are recent reports on the proinflammatory role for VIP in DSS colitis, however, other literature data are heterogenous on its expression and function in experimental colitis and IBD." (PMID 25265225, 2014). "Several pieces of evidence indicate that VIP participates in the pathophysiology of colitis and IBD." (PMID 20615234, 2010). "In the summary, this study identified that the absence of miR-30c might promote DSS-induced colitis, and the targe-regulatory effect of miR-30c on VIP might play an important role in the development of colitis." (PMID 38342939, 2024). "Similarly, VIP treatment ameliorates the phenotype of DSS colitis in VIP KO mice, while also promoting mucosal integrity via mucus secretion acceleration." (PMID 36835646, 2023). "Additionally, and in agreement with our results, it had already been described that VIP-signaling induces a reduction in MMP9 expression in rodent models of colitis and lung damage as well as in fibroblastic synoviocytes from patients with osteoarthritis." (PMID 34944693, 2021). "This fact has been observed in the following experimental designs: On one hand and in the context of gastrointestinal inflammation, VIP knock-out mice showed a more severe phenotype in DNBS- and DSS-induced colitis in mice and VIP has been linked to the maintenance of intestinal integrity." (PMID 34322118, 2021). "We focused on β-endorphin, vasoactive intestinal peptide (VIP), neurotensin, enkephalins, substance P and bradykinin because these peptides are linked to pain sensitization or inflammation and, as such, are relevant in the pathophysiology of colitis." (PMID 34639054, 2021). "In TNBS-colitis, VIP KO mice are resistant to colitis with lower levels of TNF-α and IL-6103." (PMID 31559013, 2019). "At clinical and histological levels, VIP and nanoparticles of VIP treatment decreased the pro-inflammatory cytokine profile in the colon, reducing tight junction and ion-transporter protein expression associated with severe DSS colitis." (PMID 31861827, 2019). "VIP treatment recovered the phenotype, protecting VIP-KO mice against DSS colitis." (PMID 31861827, 2019). "VIP also ameliorates bacterial infection-induced intestinal barrier disruption by preventing the translocation of tight junction proteins ZO-1, occludin, and claudin-3 in aCitrobacter rodentium-induced colitis model." (PMID 31559013, 2019). "However, higher concentrations of VIP can lead to worsening of TNBS-colitis as well as impaired barrier function, at least in vitro." (PMID 25932952, 2015). "Similarly, treating VIPKO mice with exogenous VIP protected IEC dynamics and goblet cell secretary capacity, reducing susceptibility to DSS-induced colitis." (PMID 25932952, 2015). "In conclusion, VIP plays a crucial role in the development and maintenance of colonic epithelial barrier integrity under physiological conditions and promotes epithelial repair and homeostasis during colitis." (PMID 25932952, 2015). "The colitis model mice exhibited the opposite results, in which the highest concentrations were observed for ET-1 (19.21 ± 1.02 pg/mL) and SP (63.02 ± 2.19 pg/mL), and the lowest concentrations were found for SS (22.47 ± 2.01 pg/mL) and VIP (25.79 ± 1.23 pg/mL)." (PMID 32849906, 2020). "Besides, VIP can also influence certain immune aspects of colitis." (PMID 32849906, 2020). "Interestingly, LP-YS4 could significantly (P < 0.05) improve the serum concentrations of SS and VIP in colitis mice and markedly decrease those of ET-1 and SP." (PMID 32849906, 2020).